APC (APC regulator of Wnt signaling pathway)
Diseases named in the same sentence as APC in open-access papers (continued):
Sharing a sentence is not in itself a finding about the gene and the disease.
Familial adenomatous polyposis (continued). "FAP is a hereditary cancer syndrome caused by germline mutations in the APC (adenomatous polyposis coli) gene predisposing to hundreds of adenomatous polyps of the colon and colorectal adenocarcinoma as well as, to a lesser extent, to other cancer types." (PMID 32752153, 2020). "The APC gene was first characterized as a crucial tumor suppressor gene of the distal gastrointestinal tract, with germ-line mutations in APC resulting in familial adenomatous polyposis." (PMID 32586050, 2020). "Background and objectives: Familial adenomatous polyposis is one of the APC-associated polyposis conditions described as genetically predetermined colorectal polyposis syndrome with a variety of symptoms." (PMID 31547110, 2019). "For instance, individuals with familial adenomatous polyposis are at increased risk of colon cancer due to one mutated copy of the APC gene." (PMID 30811346, 2019). "APC-associated polyposis conditions include three main clinical phenotypes of polyposis: familial adenomatous polyposis (FAP), attenuated FAP (AFAP), and gastric adenocarcinoma and proximal polyposis of the stomach (GAPPS)." (PMID 31547110, 2019). "Germline mutations in the tumor suppressor Adenomatous Polyposis Coli (APC) define Familial Adenomatous Polyposis (FAP), the genetic predisposition to developing adenomatous polyps." (PMID 31231471, 2019). "The CTNNB1 gene, which encodes beta-catenin, is the most frequently mutating gene in exon 3 in HB; consequently, an adenomatous polyposis coli (APC) germline mutation in HB has been associated with a familial adenomatous polyposis history." (PMID 31547062, 2019). "High polyposis penetrance is associated with germ-line mutations of the APC gene at codons 1061 and 1309 in patients suffering from familial adenomatous polyposis (FAP)." (PMID 31003440, 2019). "The adenomatous polyposis coli (APC) gene is mutated in familial adenomatous polyposis and in the majority of sporadic CRCs." (PMID 31414579, 2019). "It has also been involved in familial adenomatous polyposis as a manifestation of APC gene mutation." (PMID 31417867, 2019). "Although familial adenomatous polyposis accounts for only a small fraction of colorectal cancers in the general population, APC gene mutations are the most common genetic alteration in sporadic colorectal adenocarcinomas." (PMID 31721781, 2019). "For example, familial adenomatous polyposis, a clinical syndrome associated with highly penetrant colorectal adenocarcinomas, is caused by germline mutations of APC." (PMID 31721781, 2019). "APC mutations also occur in the germline and are present in up to 85% of patients with classical familial adenomatous polyposis (CFAP)." (PMID 31382613, 2019). "Familial adenomatous polyposis is the most common hereditary polyposis syndrome, which is an autosomal dominant disease caused by a mutation in the APC gene on chromosome 5q21." (PMID 29743854, 2018). "APC is mutated in familial adenomatous polyposis (FAP), an inherited CRC syndrome, and in over 80% of sporadic colon cancer." (PMID 29419804, 2018). "Familial adenomatous polyposis (FAP) is caused by inactivating mutations in APC and MUTYH, and it is considered a risk factor for hereditary PDAC." (PMID 30134550, 2018). "Familial adenomatous polyposis (FAP) is also an autosomal dominant disorder involving mutations in the APC gene (adenomatous polyposis coli), a tumour suppressor gene and modulator of the Wnt/β-catenin pathway." (PMID 30513835, 2018). "In this study, we identified a novel germline mutation in the APC gene in members of an FAP-affected (Familial adenomatous polyposis) family." (PMID 30256815, 2018). "Overexpression of CtBP1 has also been shown to occur in adenomas from familial adenomatous polyposis patients who are hereditary colon cancer patients carrying germline APC mutations." (PMID 30410666, 2018).
Familial adenomatous polyposis (continued). "Patients with familial adenomatous polyposis (FAP) develop benign precursor lesions (polyps) early in life due to germline mutation in the APC (adenomatous polyposis coli) tumour suppressor gene." (PMID 29642622, 2018). "On the other hand, it is well-known that germline mutations in the APC gene cause Familial adenomatous polyposis." (PMID 28406434, 2017). "Transgenic ApcMin/+ mice carry an ENU-induced germline missense mutation in one allele of the APC (adenomatous polyposis coli) tumor suppressor gene which results in truncation of the Apc protein." (PMID 28881611, 2017). "Literature studies have revealed that the Adenomatous Polyposis Coli [APC] gene responsible for causing Familial Adenomatous Polyposis (FAP) is mutated at a high frequency in gastric cancer." (PMID 28144288, 2017). "Mutations in the adenomatous polyposis coli (APC) gene are responsible for Familial Adenomatous Polyposis (FAP), a genetic predisposition to colorectal cancer, and are also found in the majority of sporadic colonic tumors." (PMID 28397687, 2017). "In this study the coding region of the APC gene has been screened for mutations in a panel of 87 unrelated probands diagnosed with familial adenomatous polyposis." (PMID 26446593, 2016). "Breakdown in β-catenin regulation due to APC mutations in human patients (termed Familial Adenomatous Polyposis or FAP) leads to sporadic colorectal cancers." (PMID 27548498, 2016). "First, we searched for deleterious variants in the genes associated with adenomatous polyposis of the colon (APC, MUTYH, NTHL1, POLD1, and POLE)." (PMID 27217144, 2016). "Shortly after this initial finding, a now much more famous gene, Adenomatous Polyposis Coli (APC), which is tightly linked to Mcc on human chromosome 5q, was established as the gene responsible for hereditary colon cancer (FAP)." (PMID 27438854, 2016). "Inappropriate activation of this pathway through loss of APC function contributes to cancer progression, as in familial adenomatous polyposis." (PMID 27930734, 2016). "We previously reported that the de novo FLCN mutation occurred in descendents of patients with familial adenomatous polyposis, a disease caused by germline mutation of the APC gene." (PMID 27871249, 2016). "A majority of these tumors arise from mutations in the β-catenin gene, with a smaller proportion associated with mutations in the APC gene and familial adenomatous polyposis." (PMID 27247824, 2016). "The clinical impact of germ line mutations in APC is exemplified by the development of hundreds to thousands of adenomas, as well as carcinomas, in patients with Familial Adenomatous Polyposis (FAP)." (PMID 26970738, 2016). "Inactivating mutations in APC cause familial adenomatous polyposis and approximately 10% of patients with HB have germline APC mutations." (PMID 26116792, 2015). "Constitutional mutations inactivating one APC allele underlie the familial adenomatous polyposis (FAP) syndrome, where affected individuals often develop hundreds to thousands of colon adenomas during their second or third decades of life." (PMID 26528816, 2015). "In particular, germline mutations of the tumor suppressor gene APC are associated with familial adenomatous polyposis (FAP), and somatic mutations of the β-catenin gene (CTNNB1) are associated with sporadic desmoid tumors." (PMID 26056602, 2015). "The implication of β-catenin in malignant processes was first known for CRC, as this protein forms a complex with the APC protein, whose participation in carcinogenesis was discovered in studies of hereditary cancer caused by familial adenomatous polyposis." (PMID 25932044, 2015). "The APC gene belongs to the Wnt pathway and is somatically mutated in various cancers and also in familial adenomatous polyposis, which results from inherited APC gene mutations." (PMID 25884485, 2015).
Familial adenomatous polyposis (continued). "Previous study suggested that somatic mutation of the APC gene occurred in both sporadic colorectal carcinoma and familial adenomatous polyposis." (PMID 25617745, 2015). "Familial adenomatous polyposis is most frequently caused by pathogenic variants in either the APC gene or the MUTYH gene." (PMID 25604157, 2015). "A germ-line mutation of APC is also responsible for the genetic disorder familial adenomatous polyposis (FAP)." (PMID 26163528, 2015). "Second, mosaic pathogenic APC variants are particularly difficult to detect and probably an underestimated cause of polyposis coli." (PMID 25604157, 2015). "The four cases with cribriform-morular variant PTCs are highly suspected to be familial adenomatous polyposis; the analyses of the APC gene/genetic counseling are being conducted, and their results will be published elsewhere." (PMID 26584635, 2015). "A germ-line mutation of the APC gene causes familial adenomatous polyposis (FAP), which results in the development of multiple colorectal adenomas at an early age that unequivocally lead to CRC if no surgical interventions are taken." (PMID 26121046, 2015). "Somatic mutations in the adenomatous polyposis coli (APC) gene are frequent in fundic gland polyps from patients with familial adenomatous polyposis." (PMID 25437608, 2014). "Mutations in the Adenomatous polyposis coli (APC) gene in humans are critically involved in familial adenomatous polyposis (FAP) and represent an early genetic aberration in sporadic colorectal cancer." (PMID 24616886, 2014). "APC is a tumor suppressor gene that is mutated in patients with familial adenomatous polyposis (FAP) and the majority of sporadic colorectal cancers." (PMID 25211188, 2014). "Mutated APC can cause familial adenomatous polyposis and is mutated in the vast majority of all sporadic colorectal cancers." (PMID 24817781, 2014). "Single allele germ-line APC mutations are early events that lead to familial adenomatous polyposis, a relatively benign polyp syndrome, whereas mutation of both APC alleles predisposes to high risk of CRC." (PMID 25301724, 2014). "APC-associated polyposes include Familial Adenomatous Polyposis (FAP), attenuated FAP and Turcot syndrome are all caused by germline loss of function mutations in the WNT-pathway repressor, APC." (PMID 25003333, 2014). "Mutations in the APC gene have been shown to be responsible for the autosomal dominant inherited disease, familial adenomatous polyposis (FAP)." (PMID 24959234, 2014). "Mutations in the human APC tumor suppressor gene are linked to Familial Adenomatous polyposis (FAP), an inherited cancer-prone condition in which numerous polyps are formed in the epithelium of the large intestine." (PMID 23734346, 2013). "ApcMin mice carry a mutation in the murine homolog of the human APC gene and develop multiple intestinal tubular adenomas similar to those found in patients with the familial adenomatous polyposis syndrome." (PMID 24204315, 2013). "One of the most frequently mutated genes in somatically acquired colorectal cancer is the APC tumor suppressor which, if mutated in the germline, causes familial adenomatous polyposis (FAP)." (PMID 23628112, 2013). "Familial adenomatous polyposis (FAP) linked to mutations in the APC tumor suppressor gene has also been associated with an increased risk for PC." (PMID 24303367, 2013). "Recently it was demonstrated that reduced levels of the tumor suppressor gene APC are associated with pronounced predisposition to familial adenomatous polyposis." (PMID 23383130, 2013). "This mutation was later found to be located in the APC gene, the mouse homologue of the human APC gene responsible for human familial adenomatous polyposis." (PMID 23606794, 2013).
Familial adenomatous polyposis (continued). "Modest gene expression changes can have significant biological consequences, as seen in APC gene, where 50% constitutional reductions in the expression of one allele can lead to the development of familial adenomatous polyposis." (PMID 22292045, 2012). "We interpret these events as the biallelic inactivation of a tumor suppressor gene, in particular the APC tumor suppressor gene, which is the gene responsible for familial adenomatous polyposis (FAP), and which is frequently mutated in colorectal neoplasia." (PMID 22022253, 2011). "Individuals carrying a truncating APC allele suffer from familial adenomatous polyposis (FAP), an autosomal dominant disorder characterized by hundreds to thousands of colorectal adenomas, some of which progress to cancer." (PMID 21859464, 2011). "Familial adenomatous polyposis patients with APC mutation and blocked β-catenin degradation have an overactivated Wnt signalling pathway, which results in development of hundreds of intestinal polyps, and eventually CRC." (PMID 21970873, 2011). "If this system is inactivated by bi–allelic mutations, several somatic mutations will have taken place, especially on the APC gene (Adenomatous Polyposis Coli)." (PMID 21505584, 2011). "Familial adenomatous polyposis (FAP) is an autosomal dominant CRC syndrome caused by a mutation in the APC (adenomatous polyposis coli) gene which characterizes multiple CRC." (PMID 24212791, 2011). "Similar mutations in APC in humans results in the hereditary condition familial adenomatous polyposis (FAP) in which multiple colonic polyps develop in patients, with a potential for these polyps to progress and become adenomatous or carcinomatous." (PMID 27713339, 2010). "Patients with familial adenomatous polyposis (FAP) harbor heritable mutations in the APC gene and spontaneously develop adenomatous polyps throughout their intestinal tracts at an early age." (PMID 20298593, 2010). "Germline mutations in the APC gene (chromosome 5q21) result in familial adenomatous polyposis (FAP, OMIM 175100), a dominantly inherited colorectal tumour predisposition syndrome." (PMID 19515250, 2009). "Familial adenomatous polyposis (FAP) patients heterozygous for an APC mutation frequently develop osteomas and dental anomalies." (PMID 19356224, 2009). "The selection for an optimal β-catenin signaling level for tumor formation is also supported by the spectrum of somatic mutations observed in colorectal adenomas from Familial Adenomatous Polyposis (FAP) patients with different germline mutations in APC." (PMID 19197353, 2009). "The dominantly inherited condition familial adenomatous polyposis (FAP) is caused by germline mutations in the APC gene (5q21-q22; MIM#175100)." (PMID 18433509, 2008). "The dominantly inherited condition familial adenomatous polyposis (FAP) is caused by germline mutations in the APC gene." (PMID 18433509, 2008). "Germline mutations in the adenomatous polyposis coli (APC) gene have been shown to result in the familial adenomatous polyposis (FAP) syndrome." (PMID 17411426, 2007). "Germline mutations in the APC gene are the causative factor for the Familial Adenomatous Polyposis syndrome which follows an autosomal dominant inheritance pattern." (PMID 15833136, 2005). "Familial Adenomatous Polyposis (FAP) is caused by germline mutations in the APC (Adenomatous Polyposis Coli) gene." (PMID 15833136, 2005). "In patients linked to familial adenomatous polyposis, truncations of or mutations in the APC gene are believed to enhance the progression of colorectal or gastric tumours, presumably through stabilisation of β-catenin in the cytoplasm." (PMID 14520463, 2003). "However, recent investigations have found that colonic adenomatous polyposis can be caused by several genes other than APC, which is the causative gene for FAP." (PMID 41214301, 2026).
Familial adenomatous polyposis (continued). "Possible reasons include somatic APC mosaicism, colorectal adenomatous polyposis due to non-APC causative genes, colorectal adenomatous polyposis of unknown etiology, and limitations in analytical techniques." (PMID 41214301, 2026). "It should be noted that familial adenomatous polyposis (FAP), a high-risk genetic disease for CRC, leads to multiple adenomas (an average of ≥100 per person) in patients due to Adenomatous Polyposis Coli (APC) gene mutation, with a lifetime CRC risk of nearly 100%." (PMID 41305603, 2025). "Similarly, germline APC mutations in familial adenomatous polyposis confer near-universal risk of colorectal neoplasia as well as duodenal and gastric tumors." (PMID 41303799, 2025). "For instance, familial adenomatous polyposis (FAP) could be reduced to a germline mutation in the Adenomatous Polyposis Coli (APC) gene." (PMID 41516021, 2025). "BRAF p.V600E (50%) or KRAS (p.G12V/D, 40%) mutations were present in 90% of HPs, with one other HP carrying APC p.R213* (rs587781392) which has been reported in the ClinVar database to be associated with familial adenomatous polyposis and APC-associated cancers." (PMID 40757636, 2025). "Familial adenomatous polyposis (FAP) is caused by constitutional pathogenic variants in APC." (PMID 38697781, 2024). "Patients described in literature usually present variable dysmorphic features, behavioral disturbance, and intellectual disability (ID); moreover, the involvement of the APC gene (5q22.2) in the deletion predisposes them to tumoral syndromes (Familial Adenomatous Polyposis and Gardner syndrome)." (PMID 37510409, 2023). "Notably, odontomas and supernumerary teeth can be found in patients with APC-associated familial adenomatous polyposis syndrome." (PMID 37046432, 2023). "Commensurate reductions in FXR and CDX2 resulting from inactivating APC mutations are observed in the tumor tissues of Apcmin/+ mice and familial adenomatous polyposis (FAP) patients, indicating that mutations in CRC-related genes also contribute to intestinal FXR gene silencing." (PMID 38203175, 2023). "Patients with familial adenomatous polyposis (FAP) are a high-risk group for colorectal cancer (CRC) due to a mutation in adenomatous polyposis coli (APC), a tumor suppressor gene, which causes the development of many intestinal polyps (mainly, adenoma as a precancerous lesion)." (PMID 38072949, 2023). "Supernumerary teeth are associated with malformation syndromes, including APC-associated familial adenomatous polyposis, RUNX2-associated cleidocranial dysplasia, TRPS1-associated tricho-rhino-phalangeal syndrome, ROR2-associated Robinow syndrome, and CREBBP-associated Rubinstein–Taybi syndrome." (PMID 37046432, 2023). "And CtBP2 haplo-insufficiency could rescue polyposis induced by mutation of APC in the min mouse model of the human Familial Adenomatous Polyposis." (PMID 35299743, 2022). "It was reported that CtBP2 haplo-insufficiency could rescue polyposis induced by mutation of APC in the min mouse model of the human disease Familial Adenomatous Polyposis." (PMID 35299743, 2022). "Furthermore, recent studies indicate that the incidence of MCST has increased among patients affected by familial adenomatous polyposis (FAP) due to APC germline mutations." (PMID 36428715, 2022). "While the vast majority of osteomas develops sporadically, a small subset of cases is associated with Gardner syndrome, a phenotypic variant of familial adenomatous polyposis caused by mutations in the APC gene resulting in aberrant activation of WNT/β-catenin signaling." (PMID 34725446, 2022). "Germline mutations in the APC gene lead to familial adenomatous polyposis (FAP) syndrome." (PMID 35626065, 2022). "APC gene mutations occur in familial adenomatous polyposis and are involved in many aspects of the disease progression, but the association between APC mutation status and EMC development remains unclear." (PMID 36268279, 2022).